SETP14 (SET pseudogene 14)
Gene: Processed pseudogene on chromosome 3 (155,987,304 to 155,988,176, forward strand). Ensembl gene ENSG00000240489.
Diseases named in the same sentence as SETP14 in open-access papers:
SETP14 is named in the same sentence as 1 disease in open-access papers, as found by Europe PMC text mining. Sharing a sentence is not in itself a finding about the gene and the disease.
SETP14 shares sentences with these, for which no sentence is quoted: Hypertension (1 paper).